IGFBP2 (insulin like growth factor binding protein 2)
Diseases named in the same sentence as IGFBP2 in open-access papers (continued):
Sharing a sentence is not in itself a finding about the gene and the disease.
tumor (269 papers, 1996 to 2026). "These secondary analysis results of external scRNA-seq data further confirm that these COL1A1+/COL1A2+/IGFBP2+ fibroblast-like cells are tumor associated and play a central role in the TME of brain metastasis tissues." (PMID 37479733, 2023). "This suggests that IGFBP-2 circulating levels are positively associated with tumor load and can be used to measure disease progression and response to therapy." (PMID 38137390, 2023). "Only IGFBP-2 plasma levels were associated with tumor grade, and they increased with low grade and poor differentiation (p = 0.026)." (PMID 38137390, 2023). "qRT-PCR analysis revealed that IGFBP2 levels were significantly associated with IDO mRNA amounts in clinical tumor samples (p = 0.0001, R2 = 0.6690)." (PMID 36556226, 2022). "PCa cells produce significantly high amount of IGFBP2, and the serum level of IGFBP2 is positively correlated with the tumor grades and stages, suggesting the potential role of IGFBP2 as a biomarker in PCa risk, resistance and relapse." (PMID 35328346, 2022). "CHI1L3, Serpin E1 and IGFBP2 are all associated with an increase in monocyte abundance in tumour tissue." (PMID 36430641, 2022). "This is reinforced by the observation that genes (Igfbp1 and Igfbp2) encoding insulin like growth factor binding proteins and insulin-induced gene 1 (Insig1) were downregulated in tumor of KO mice." (PMID 34685767, 2021). "It has been previously reported that increased serum levels of IGFBP2 are linked with tumor grades and stages, predicting a higher recurrent risk and a shortened OS in OC." (PMID 33282953, 2020). "In other tumor types, IGFBP2 has been reported to predict risk of relapse and resistance to therapy, with IGFBP2 autoantibodies detectable both in early stage and metastatic patients." (PMID 32093404, 2020). "Insulin-like growth factor-binding protein 2 (IGFBP2) is a tumor-associated protein measurable in patients’ biopsies and blood samples." (PMID 32093404, 2020). "For example, Plasma IGFBP-2 levels were significantly correlated with tumor volume and independently associated with poor overall survival in patients with GBM." (PMID 32684847, 2020). "IGFBP2 expression in the tumor has been proved in many researches that was associated with a variety of pathological conditions, including hypoxia and regeneration." (PMID 31138764, 2019). "Several findings have suggested the tumor-promoting role of IGFBP-2 in GBM and its association with a poor prognosis." (PMID 28323865, 2017). "Our previous study showed that the plasma of patients of low grade tumors contained a higher level of IgG autoantibodies against tumor-associated antigen IGFBP2 than that of high grade tumor patients." (PMID 27738332, 2016). "IGFBP2, which was linked with both patient death and tumor recurrence in our analysis, was another interesting hit, as it has been associated with a number of cancer types but few studies have addressed its role in CRC26–28." (PMID 26097693, 2015). "IGFBP2 levels were mildly but significantly associated with tumor size and were significantly higher in stage IV than stage I or III disease." (PMID 24069370, 2013). "Although overexpressed IGFBP-2 is associated with increased tumor stages and grades, relapse, metastasis and prognosis in advanced cancers, it is less satisfactory in diagnosing early cancers." (PMID 23165420, 2013). "Clinically, serum exosomal IGFBP2 levels correlated with tumor grade and could serve as a diagnostic biomarker." (PMID 41620401, 2026). "This is evidenced by the regulatory role of IGFBP2 in genes associated with tumor cell growth." (PMID 40935839, 2025). "Importantly, tumor-derived ImpL2/IGFBP2, Upd3/interleukin, and other ligands that result in lipid loss and muscle dysfunction have been consistently found in other tumor-bearing flies and mammals." (PMID 39924534, 2025). "IGFBP2 has been implicated in promoting tumor growth and progression in several types of cancer." (PMID 38378721, 2024).
tumor (continued). "IGFBP2 has been recently implicated in the progression and metastasis of several tumour types." (PMID 38605363, 2024). "Studies have demonstrated that low IGFBP-3 and high IGF-1 and IGFBP-2 levels are associated with high cancer risk, poor prognosis, and tumor metastasis in several cancers, including CRC, breast cancer, and prostate cancer; however, these findings remain controversial and can be population specific." (PMID 38137390, 2023). "Tumor progression may be also facilitated by the overexpression of insulin‐like growth factor binding protein‐1 (IGFBP2) and functional deficiencies in DNA‐dependent protein kinase proteins." (PMID 37814403, 2023). "However, the role of IGFBP2 in dysfunctional mammary adipocytes and the link to cancer is unclear, as it has been associated with both tumor progression and suppression." (PMID 37436978, 2023). "Additionally, more significant tumor sizes and lower OS rates were linked to higher plasma IGFBP-2 levels, demonstrating that IGFBP-2 may function as a prognostic and diagnostic biomarker for CRC." (PMID 37719843, 2023). "Despite the inverse relationship between tumour IGFBP-2 abundance and survival, the mechanistic basis and functional consequences are poorly understood." (PMID 40429889, 2025). "While matrisome transcripts like ITGA5 and LGALS3 were enriched in TCs and infiltrating stromal cells residing around necrotic regions, the hypoxic tumor regions revealed enhanced expression of IGFBP2 and COL20A1." (PMID 41366031, 2025). "There were several transcripts showing elevated expression in GBM stromal cell types versus stromal cell types in the grade III tumor, including IGFBP2 (ECM glycoprotein), ANXA1 (ECM-affiliated), ITGA7 (integrin), and SRGN (proteoglycan)." (PMID 41366031, 2025). "Due to its role in tumor progression, IGFBP2 has also been studied extensively as a tumor biomarker." (PMID 40443651, 2025). "The expression level of IGFBP2 in numerous tumor samples is significantly downregulated, aligning with the findings of our study analysis." (PMID 39854135, 2025). "Highly expressed in the hepatic tissue, adipocytes, and central nervous system, IGFBP2 plays pivotal roles in tumor growth, metabolism, and progression, positioning it as a potential biomarker across multiple cancers." (PMID 40821817, 2025). "IGFBP2 (Insulin-like Growth Factor Binding Protein 2) acts as an oncogene, promoting tumor growth, migration, and invasion, and it can serve as a potential therapeutic target and biomarker." (PMID 41012124, 2025). "Separately, it has been observed that CAFs can suppress the insulin‐like growth factor‐1 receptor (IGF‐1R) signaling through their distinct secretome, particularly via abundant IGFBP2, thereby sensitizing resistant tumor cells to conventional antitumor agents." (PMID 41498024, 2025). "IGF-2 and IGFBP2 secreted by tumor cells upregulate the glycolytic pathway of bone marrow stromal cells and promote tumor cell proliferation and metastasis." (PMID 40165895, 2025). "Simultaneously, the arginine-glycine-aspartic acid (RGD) sequence allows IGFBP-2 to interact with integrins, affecting cellular processes like migration, survival, and tumor progression." (PMID 39585162, 2024). "This context-dependent behavior of IGFBP-2 is a key factor in its varied effects across different tumor microenvironments." (PMID 39585162, 2024). "In accordance with the methodology and parameter settings of a previous study, we conducted single-cell analysis to examine IGFBP-2 expression in tumor cells, utilizing scRNA-Seq data from 9 patients in the GSE138794 dataset." (PMID 39138166, 2024). "Our data are consistent with recent reports in other cancers that reveal the importance of IGFBP2 in tumor growth and metastasis, and we identify aged stromal fibroblasts as a significant source of IGFBP2 in the aged TME." (PMID 39007351, 2024).
tumor (continued). "The results showed a significant elevation in plasma IGFBP-2 levels among GBM patients compared to non-tumor controls, consistent with the results obtained from IHC." (PMID 39138166, 2024). "IGFBP2 is a secreted protein which prevents IGF-I/-II binding to their receptors, and it is also implicated in the regulation of tumor microenvironment (TME) in a macrophage-dependent manner." (PMID 38918360, 2024). "Proteolytic cleavage, primarily mediated by matrix metalloproteinases (MMPs) and other proteases, diminishes IGFBP-2’s affinity for IGFs in the tumor microenvironment, thereby increasing free IGFs and facilitating tumor cell proliferation and survival." (PMID 39585162, 2024). "IGFBP-2 can also act intrinsically by interacting with integrin receptors, which can involve regulation of downstream effectors such as the tumour suppressor genes PTEN, STAT3, and NFκB." (PMID 38893232, 2024). "IGFBP2 is involved in regulating signals that promote tumor progression, contributing to the pro-tumorigenic characteristics of cancer cells." (PMID 38339384, 2024). "High IGFBP-2 level was related to rapid tumor growth and shorter survival time indicating low expression of SVIP and high expression of STUB1 in GBM cells." (PMID 39138166, 2024). "IGFBP2 promotes tumor progression by inducing the alternative polarization of macrophages through the STAT3 pathway." (PMID 39335579, 2024). "For instance, IGFBP-2 can inhibit tumor growth by modulating IGF signaling or interacting with tumor suppressor proteins like phosphatase and tensin homolog (PTEN)." (PMID 39585162, 2024). "We analyzed the tumor lysates from young and aged animals and observed an increase in both Igfbp2 and Akt signaling." (PMID 39007351, 2024). "While IGFBP2 and CP displayed more expression in the cellular tumor zone toward the tumor center, LOX was expressed in the vascular regions at the periphery." (PMID 38339384, 2024). "It was inconsistently reported that high IGF-1 and IGFBP-2 and low IGFBP-3 circulating levels are associated with high cancer risk, poor prognosis, and tumor metastasis in several cancers." (PMID 38137390, 2023). "IGFBP2 has been shown to regulate the activity of immune cells, such as macrophages and T cells, in the tumor microenvironment." (PMID 37928523, 2023). "Studies have shown that IGFBP2 can ameliorate tumor hypoxic conditions by promoting vascular neovascularization in the tumor microenvironment." (PMID 38148838, 2023). "Recent evidence suggests that Insulin-like growth factors (IGF) Binding Protein-2 (IGFBP-2) plays an important role in promoting tumor growth." (PMID 37046342, 2023). "IGFBP2 promotes tumor growth and metastasis by enhancing cell proliferation, survival, and migration." (PMID 37928523, 2023). "In our study cohort, IGFBP-2 levels were higher in patients with CRC than they were in the controls, and IGFBP-2 levels increased with increasing histological grade of tumor differentiation." (PMID 38137390, 2023). "In this study, we provide evidence that IGFBP2 is significantly overexpressed in HCC tumor tissues and its expression levels correlate with several mesenchymal biomarkers, while exhibiting a negative association with epithelial markers." (PMID 37957694, 2023). "Increased circulating levels of IGFBP-2 have been detected in both the serum and tumor tissues of most cancers including CRC, and this has been shown to be associated with worse prognosis." (PMID 38137390, 2023). "In vitro studies have confirmed that IGFBP2 is involved in regulating the proliferation, invasion, and metastasis of tumor cells." (PMID 38099574, 2023). "It has been previously reported that IGFBP2 mediates tumor cell metastasis in different cancer types." (PMID 37029430, 2023). "Consistent with its oncogenic effects, high IGFBP-2 expression in tumor tissues correlates with poorer prognosis." (PMID 38137505, 2023).
tumor (continued). "It should be noted that gene expression of all m6A regulators, except IGFBP2, was increased in tumor samples, and most of them were statistically significant." (PMID 37952076, 2023). "Circulating levels of IGF-1, IGFBP-2, and IGFBP-3 were investigated for their association with tumor grade and stage." (PMID 38137390, 2023). "IGFBP2 promotes tumor cellular proliferation, migration, invasion, angiogenesis, epithelialtomesenchymal transition and is highly elevated in serum or tissue in patients with malignant tumors." (PMID 37784035, 2023). "This presents an exciting opportunity for the restoration of IGFBP2 into the cancer microenvironment to further contain the primary tumor." (PMID 37436978, 2023). "The TCGA database was used to identify expression patterns of IGF2BPs and showed that in PTC tumor samples IGF2BP3 were expressed in low levels while IGFBP2 was highly expressed, IGF2BP1 has barely any difference, compared to normal samples." (PMID 38092752, 2023). "For instance, COL11A1 stimulates NK-κB/insulin-like growth factor binding protein 2 (IGFBP2) to induce TGF-β3 activation in ovarian CAFs to promote tumor growth." (PMID 36906534, 2023). "Having established that IGFBP2 reduces SHH MB tumor cell migration and levels of EMT markers, we next wished to determine the signaling mechanisms downstream of IGFBP2 regulating these phenotypes." (PMID 37029430, 2023). "Subsequent Western blot and immunohistochemistry analyses of the tumor tissues revealed lower expression of E-cadherin and higher expression of N-cadherin and vimentin in response to IGFBP2 overexpression." (PMID 37957694, 2023). "Regarding tumor purity, the expression of IGFBPs negatively correlated with tumor purity, except for IGFBP2 in PCPG, KIRP, and OV (p < 0.05)." (PMID 37199034, 2023). "Consistently, Western blot analysis demonstrated a significant upregulation of IGFBP2 expression in tumor tissue compared to adjacent tissue in five out of the six tested sample pairs (P < 0.001)." (PMID 37957694, 2023). "In this study, we aimed to determine the circulating levels of IGF-1, IGFBP-2, and IGFBP-3 in patients with CRC and to investigate their association with different clinical aspects of CRC, including risk, tumor grade, and tumor stage." (PMID 38137390, 2023). "Immunohistochemical analysis revealed robust expression of IGFBP2 in tumor tissues of HCC patients, whereas its expression was seldom detected in para-carcinoma tissues." (PMID 37957694, 2023). "The data here indicates that the stem-like cellular compartment demonstrates decreased capability to recruit anti-tumour immune populations, while retaining the ability to engage other immune populations through sVCAM-1 and IGFBP2 production." (PMID 36430641, 2022). "It was suggested that IGFBP2 contributes to immune events in PDAC because it induces tumor progression via the enhancement of alternative macrophage polarization by regulating STAT3 signaling." (PMID 36556226, 2022). "IGFBP2 is considered a multifunctional oncogenic protein with tumor promoting functions through multiple signaling pathways in many cancers." (PMID 36556226, 2022). "Individuals highly expressing IGFBP2 (++/+++) had increased tumor volumes and more advanced T stage compared with the low IGFBP2 group (−/+)." (PMID 36556226, 2022). "In this study, we provide evidence that IGFBP2 increases Treg recruitment and tumor progression in PDAC patients." (PMID 36556226, 2022). "As is evident from WB and IHC results that IGFBP2 was significantly higher in the six tumor tissues than in the paired adjacent tumor tissues." (PMID 36110851, 2022). "Clinicopathological assessment demonstrated tumor IGFBP2 expression had a significant correlation with T stage." (PMID 36556226, 2022). "It has been confirmed that IGFBP2 can induce tumor epithelial–mesenchymal transformation and metastasis through the NF-κB signaling pathway." (PMID 36778912, 2022).
tumor (continued). "Stimulation of IGFBP-2 expression by HOTAIR appears to mediate this effect, since enhanced cell migration and tumor growth in vivo resulting from HOTAIR overexpression was reversed by IGFBP-2 silencing." (PMID 35597813, 2022). "Numerous findings indicate IGFBP2 always leads to an immunosuppressive microenvironment and tumor progression." (PMID 36556226, 2022). "Tumor malignant phenotype related IGFBP2 and KRT18 were significantly enriched in KRAS-Mut subtype, whereas neutrophils and macrophages related CD177, MMP1 and ARG1 were enriched in WT subtypes." (PMID 35836817, 2022). "Growing evidence indicates that IGFBP2 plays an essential role in several key oncogenic processes, such as tumor cellular proliferation, epithelial to mesenchymal transition, stemness, invasion, angiogenesis, immunoregulation, and migration." (PMID 34035992, 2021). "IGFBP2 is a known factor for malignancy and aggressiveness in different tumor entities regarded as a biomarker, which seems to be in line with the biomarker function of MACC1." (PMID 34830078, 2021). "IGFBP2 has been described to be overexpressed by CRC patients, thus IGFBP2 levels were positively related to tumor load and clinical pathological parameters." (PMID 34830078, 2021). "In TCGA data, the average IGFBP1/3/7 expression levels in STAD were significantly higher than those in normal tissue, while IGFBP2/5/6 expression was significantly lower in tumor tissue." (PMID 34745945, 2021). "In this study, we will focus on the insulin-like growth factor binding protein 2 (IGFBP2), a recently discovered multitasked gene regulated by DNA methylation which has also been reported to function both as a tumor-promoting and -suppressing gene." (PMID 34434494, 2021). "Aberrant expression of SDCBP in some cancers has been associated with tumor progression, metastatic dissemination, and poor prognosis via FAK, Src, p38-MAPK, AKT, NFκB, IGFBP2, EGFR, and VEGFR." (PMID 34638436, 2021). "In order to study the effect of targeting IGFBP2 promoter DNA methylation on cell plasticity, we proceeded by conducting similar experiments in two epithelial tumor cells lines (H3122 and MCF7)." (PMID 34434494, 2021). "This work also proposes a novel mechanism of gene dysregulation by IGFBP2 by modulating a key molecule of tumor invasiveness and progression—FRA-1 TF." (PMID 34211498, 2021). "Our ‘in-house’ RNAseq data demonstrate that increased PLEKHS1 expression is significantly associated with high-risk NMIBC (in both G3T1 tumours and CIS) and significant reductions in the expression of IGFBP-2, IGFBP-4, and IGF-1R." (PMID 34681810, 2021). "Integrins have been described as cellular collectors for extracellular IGFBP2 to transmit the pro-tumorigenic signaling into the cell, e.g., by inhibiting the tumor suppressor activity of PTEN." (PMID 34830078, 2021). "The IGF-independent activities of IGFBP2 appear complex in an oncogenic network, affecting a series of signaling pathways for tumor growth and progression." (PMID 34830078, 2021). "A critical analysis of this gene regulatory network gives insights into the mechanism of gene regulation by IGFBP2 via several TFs including the key molecule of GBM tumor invasiveness and progression, FRA-1." (PMID 34211498, 2021). "Meanwhile, IGFBP2 is regarded as a biomarker in multiple solid cancers indicating high tumor proliferation, invasiveness, and metastatic activities." (PMID 34830078, 2021). "Following androgen withdrawal, higher IGFBP-2 mRNA expression promotes androgen-independent tumour growth, and also correlates with a higher Gleason score." (PMID 32056047, 2020). "It was also assumed that the immunohistochemical methods used for the detection of IGFBP2 in tumor sections recognized its cleaved forms as well." (PMID 32133294, 2020). "In contrast to these studies, IGFBP2 behaves as tumor suppressor in our experiments: it inhibits the IGF1-induced proliferation and the pro-survival PI3K/Akt pathway in 4T1 cells." (PMID 32133294, 2020).